SETMAR (SET and mariner transposase domain methyltransferase)
Diseases named in the same sentence as SETMAR in open-access papers:
SETMAR is named in the same sentence as 19 diseases in open-access papers, as found by Europe PMC text mining. Sharing a sentence is not in itself a finding about the gene and the disease. The quoted sentences say what the papers report.
glioblastoma (6 papers, 2017 to 2022). The most malignant astrocytic tumor (WHO grade IV). "Dysregulation of SETMAR expression has been associated with several cancers, including glioblastoma, leukemia, hematologic neoplasms, breast and colon cancer, and mantle cell lymphoma." (PMID 34947873, 2021). "Another study in glioblastoma cell lines reported that knockdown of SETMAR by shRNA or siRNA is associated with a decreased H3K36me2 level." (PMID 34947873, 2021). "In glioblastoma tissues, the shorter isoform of SETMAR (S-SETMAR) was predominant over the full-length isoform (FL-SETMAR), and the expression of both SETMAR variants was higher in the tumor compared to the perilesional tissues." (PMID 35047379, 2021). "Accordingly, SETMAR protein has been searched in tumor from patients, such as hematologic neoplasms, gliomas and glioblastomas." (PMID 35395947, 2022). "Until recently, the presence of SETMAR proteins in tumor tissues from patients was addressed only in glioblastomas (GBM)." (PMID 35395947, 2022). "Recent evidence suggests that the chimeric protein SETMAR is a factor of interest in cancer, especially in glioblastoma." (PMID 35047379, 2021). "This is consistent with reports that SETMAR stimulates cellular proliferation and suppresses apoptosis, and that it is up-regulated in several diseases including glioblastomas, leukemias, breast and colon cancers." (PMID 30329085, 2019). "In addition, SETMAR is dysregulated in several cancers, such as glioblastoma, leukemia, hematologic neoplasms, breast and colon cancer, and mantle cell lymphoma." (PMID 34947873, 2021). "Most importantly, expression of SETMAR increased in leukemias, breast cancer and glioblastoma." (PMID 34604366, 2021). "Four SETMAR proteins may thus be synthesized in human glioblastomas, each having potentially different biochemical properties and characteristics." (PMID 28038463, 2017). "SETMAR (SET Domain and Mariner Transposase fusion gene) has been pointed out as a protein of interest in the study of different cancers, including Glioblastoma (GB, World Health Organization grade IV gliomas)." (PMID 35047379, 2021). "However, little is known about the expression of this protein in glioblastoma tissues, and no study has been done to assess if SETMAR could be a prognostic and/or diagnostic marker of glioblastoma." (PMID 35047379, 2021).
breast carcinoma (5 papers, 2010 to 2021). "On the treatment side, knockdown of SETMAR increases the sensitivity of leukemia cell lines to etoposide and of breast cancer cell lines to the anthracycline Adriamycin." (PMID 34947873, 2021). "We found that for seven HMTs (KMT2C, SETDB2, SETD2, SETMAR, PRDM1, PRDM5, and PRDM8), copy number amp/gain or deletion was significantly associated (p<0.05) with shorter survival in breast cancer patients." (PMID 25537518, 2015). "Moreover, SETMAR has been described as mediating resistance to Topoisomerase II inhibitors in breast cancer cells." (PMID 28038463, 2017). "In addition to its roles in chromatin dynamics and genome plasticity, a positive correlation was established between SETMAR overexpression and certain cancers (leukemia, breast cancer..)." (PMID 28038463, 2017). "In addition, SETMAR interaction with TOP2A has been found to enhance TOP2A function in chromosome decatenation and to promote resistance to topoisomerase II inhibitors in breast cancer cells." (PMID 34947873, 2021).
bladder cancer (4 papers, 2021 to 2022). "In bladder cancer cells, expression of the full-length SETMAR has been associated with an inhibition of lymph node metastasis via an increase in H3K27me3 at the promoters of metastatic oncogenes, inhibiting their transcription." (PMID 34947873, 2021). "A recent study in bladder cancer found that SETMAR could also mediate H3K27me3, a mark associated with heterochromatin and gene repression." (PMID 34947873, 2021). "SETMAR pre‐mRNA, for example, was reported to be alternatively spliced to two protein isoforms in bladder cancer by NONO, leading to lymphatic metastasis." (PMID 36394206, 2022). "Two splicing factors have been found to regulate SETMAR alternative splicing, NONO and SFPQ, in bladder cancer." (PMID 34947873, 2021).
colon cancer (2 papers, 2019 to 2021). "The Notch signaling pathway, involved in developmental and homeostatic processes, also regulates SETMAR expression as knockdown of each of the four Notch receptors decreases SETMAR expression in colon cancer stem cells." (PMID 34947873, 2021). "Excluding the regulation of SETMAR expression by the Notch signaling pathway in colon cancer stem cells, SETMAR has not been directly connected to any other specific cell signaling pathway." (PMID 34947873, 2021).
mantle cell lymphoma (2 papers, 2010 to 2021). Mantle cell lymphoma is a rare form of malignant non-Hodgkin lymphoma affecting B lymphocytes in the lymph nodes in a region called the ``mantle zone''. "Among these genes, DBN1, SETMAR and HIG2 were found to be significantly correlated to SOX11 expression in two cohorts of primary mantle cell lymphomas." (PMID 21124928, 2010).
thyroid cancer (2 papers, 2024 to 2025). "Numerous enzymes that are involved in histone methylation, such as SETMAR, have been found to be associated with the differentiation of thyroid cancer." (PMID 38900084, 2024). "To further assess the role of SETMAR methyltransferase activity in thyroid cancer differentiation, we overexpressed a methyltransferase‐deficient mutant of SETMAR, SETMAR‐D248S, in ATC cells." (PMID 38900084, 2024). "Correspondingly, the expression level of SETMAR was significantly associated with various clinical characteristics of thyroid cancer, including clinical stage, T stage, lymph node metastasis, BRAFV600E mutation, disease‐free survival, and progression‐free survival." (PMID 38900084, 2024). "To investigate the mechanism by which SETMAR regulates gene expression, we performed CUT&Tag experiments to determine the genome‐wide target sites of SETMAR in thyroid cancer cells." (PMID 38900084, 2024). "In this study, we identified SETMAR as a differentiation‐related histone methylation modifier in thyroid cancer, and we found that its mRNA was stabilized by METTL3‐mediated m6A modification in an IGF2BP3‐dependent manner." (PMID 38900084, 2024). "In summary, these results demonstrated the crucial role of SETMAR in regulating the differentiation of thyroid cancer." (PMID 38900084, 2024). "The results showed that the expression of SETMAR in thyroid cancer cells was lower than that in normal thyroid cells, especially in ATC cells." (PMID 38900084, 2024). "Correspondingly, the overexpression of SETMAR reduced the migration and invasion of thyroid cancer cells, while SETMAR knockdown enhanced these abilities in tumor cells." (PMID 38900084, 2024). "To further investigate the regulatory effect of SETMAR on the differentiation of thyroid cancer, we overexpressed SETMAR in two ATC cell lines (CAL‐62 and BHT101) that had relatively low levels of endogenous SETMAR expression." (PMID 38900084, 2024). "The GSEA results showed that overexpression of SETMAR can significantly promote the differentiation of thyroid cancer cells." (PMID 38900084, 2024). "The overexpression of SETMAR in thyroid cancer cells increased their sensitivity to DOX treatment to a certain extent, whereas SETMAR knockdown reduced this sensitivity." (PMID 38900084, 2024). "Our study revealed the key epigenetic mechanism by which SETMAR regulates the differentiation of thyroid cancer cells." (PMID 38900084, 2024). "Taken together, these findings suggest that SETMAR is involved in regulating various biological behaviors of thyroid cancer." (PMID 38900084, 2024). "More importantly, we utilized the METTL3‐14‐WTAP activator to restore SETMAR expression and promote the differentiation of thyroid cancer, thus providing a new method of redifferentiation therapy for treating patients with thyroid cancer." (PMID 38900084, 2024). "Our findings revealed that only the global abundance of H3K36me2 was altered in thyroid cancer cells as the expression of SETMAR changed." (PMID 38900084, 2024). "To confirm that SETMAR promotes thyroid cancer differentiation by regulating SMARCA2, we transfected shRNAs against SMARCA2 into SETMAR‐overexpressing ATC cells." (PMID 38900084, 2024). "In the present study, we first identified SETMAR as an activator that promotes the differentiation of thyroid cancer cells, and its expression level is markedly decreased with increasing thyroid dedifferentiation." (PMID 38900084, 2024). "In contrast, the knockdown of SETMAR in vitro significantly reduced the expression of differentiation markers in thyroid cancer cells, increased proliferation and decreased radioactive iodine uptake." (PMID 38900084, 2024). "METTL3-14-WTAP activators can restore SETMAR expression, promoting thyroid cancer differentiation." (PMID 40819127, 2025).
thyroid cancer (continued). "The results revealed that overexpression of SETMAR in vitro effectively enhanced the expression of differentiation markers in thyroid cancer cells, leading to inhibition of thyroid cancer proliferation and increased radioactive iodine uptake." (PMID 38900084, 2024). "Finally, the METTL3‐14‐WTAP activator effectively facilitates the redifferentiation of thyroid cancer cells via the SETMAR‐SMARCA2‐TTF axis utilized." (PMID 38900084, 2024). "In this study, SETMAR as a key gene that affects thyroid cancer differentiation is identified." (PMID 38900084, 2024). "Based on these findings, we speculated that SETMAR may enhance the differentiation of thyroid cancer by activating the function of the SWI/SNF complex." (PMID 38900084, 2024). "In light of these results, we hypothesized that METTL3‐mediated m6A modifications are involved in controlling SETMAR expression and thus enhancing thyroid carcinoma differentiation." (PMID 38900084, 2024). "Therefore, SETMAR-activated SMARCA2 enhances chromatin accessibility for the active expression of thyroid differentiation transcription factors through chromatin remodeling to regulate thyroid cancer differentiation." (PMID 40819127, 2025). "In addition, we found that the dysregulation of SETMAR during thyroid cancer dedifferentiation is caused by a lack of METTL3‐mediated N6‐methyladenosine modification which maintains the stability of SETMAR mRNA." (PMID 38900084, 2024). "Thus, SETMAR is a promising therapeutic target and prognostic marker for thyroid cancer." (PMID 38900084, 2024). "We found that overexpression of SETMAR could promote the protein and mRNA expression of SMARCA2 in thyroid cancer cells, while inhibition of SETMAR had the opposite effect." (PMID 38900084, 2024). "In conclusion, the expression of SETMAR in thyroid cancer is stabilized by METTL3‐mediated m6A modification in an IGF2BP3‐dependent manner, which could explain its dysregulation during dedifferentiation of thyroid cancer." (PMID 38900084, 2024). "SETMAR significantly regulates the proliferation, epithelial‐mesenchymal transformation (EMT), thyroid differentiation‐related gene expression, radioactive iodine uptake, and sensitivity to MAPK inhibitor‐based redifferentiation therapies of thyroid cancer cells." (PMID 38900084, 2024).
lung adenocarcinoma (1 paper, 2024). A carcinoma that arises from the lung and is characterized by the presence of malignant glandular epithelial cells. "At the same time, we analyzed the mutation rates of H3K36 enzymes (including NSD1, NSD2, NSD3, ASH1L, SMYD2, SETDB2, SETD3, and SETMAR) in lung adenocarcinoma, which showed that the amplification mutation frequency of H3K36 enzymes was at a low level." (PMID 39119928, 2024).
papillary thyroid carcinomas (1 paper, 2024). "SETMAR expression was significantly lower in classic papillary thyroid carcinomas (CPTCs) than in normal tissues, and high‐cell variant PTCs, which are associated with more aggressive clinical behavior, exhibited even lower levels of SETMAR expression than CPTCs." (PMID 38900084, 2024).
cancer (10 papers, 2017 to 2024). A tumor composed of atypical neoplastic, often pleomorphic cells that invade other tissues. "SETMAR has been reported to be a protein lysine methyltransferase that mediates methylation of H3K27 and H3K36, and dysregulation of SETMAR has been associated with several cancers." (PMID 37237385, 2023). "In addition, transcriptional variants of SETMAR show a broad expression pattern in human diseases including cancer." (PMID 34377368, 2021). "In cancer cells, the SETMAR gene is over-expressed, and FL-SETMAR then sustains oncogenic processes and the development of cancer cells or cancer stem cells." (PMID 35395947, 2022). "In cancer cells, the SETMAR gene is over-expressed, and the full length SETMAR sustains oncogenic processes." (PMID 35395947, 2022). "The role of each SETMAR protein has to be defined, but a first line of evidences suggests that S-SETMAR is preferably expressed in cancer stem cells, whereas FL-SETMAR is preferentially expressed in differentiated cells." (PMID 35395947, 2022). "SETMAR is overexpressed in many cancers (leukemia, hematologic neoplasms, Mantle cell lymphoma, breast and colon cancers), including in GBs." (PMID 35047379, 2021). "It thus appeared interesting to develop SETMAR inhibitors to improve cancer treatments." (PMID 35395947, 2022). "In addition, SETMAR, via its role in the NHEJ pathway, is important in the survival of glioblastoma cancer cells to radiation therapy, which can cause cancer relapse." (PMID 34947873, 2021). "In addition, SETMAR is dysregulated in different types of cancer, indicating a potential pathological role." (PMID 34947873, 2021). "Misregulation of SETMAR expression could therefore be involved in tumorigenesis by altering gene expression, affecting how cancer cells respond to drug treatment and promoting DNA repair through the NHEJ." (PMID 30329085, 2019). "In addition, a specific inhibitor could potentially be clinically relevant, by itself or in combination, as SETMAR is dysregulated in several cancers." (PMID 34947873, 2021). "The expression of SETMAR has been found to be regulated by SOX11, a transcription factor involved in development, including neurogenesis and skeletogenesis, and disease, such as neurodevelopmental disorders, osteoarthiritis, and cancers." (PMID 34947873, 2021). "However, the role of SETMAR in regulating cancer cell differentiation has not been previously investigated." (PMID 38900084, 2024). "However, it is striking that the expression pattern of the endogenous SETMAR proteins, and especially which isoforms were expressed in cancer cells, had never been studied." (PMID 28038463, 2017).
tumor (7 papers, 2014 to 2024). "These associations highlight how SETMAR’s chromatin binding fine-tune gene regulatory networks in human tumour cells." (PMID 34377368, 2021). "Moreover, in the PTC cohort, SETMAR expression was correlated with clinical stage, tumor size, lymph node metastasis, and BRAFV600E mutation." (PMID 38900084, 2024). "The results indicated that the TDS level and SETMAR expression were lower in tumor cells, particularly in ATC cells." (PMID 38900084, 2024). "The results indicated that the expression of SETMAR in tumor tissues was significantly lower than that in normal tissues, and its expression level was notably lower in relatively poorly differentiated tumors." (PMID 38900084, 2024). "To address this question, we next analyzed the expression patterns of all SETMAR isoforms in different areas of primary GB tumors, including the perilesional, tumor and necrotic areas." (PMID 35047379, 2021). "We find that SETMAR is recurrently underexpressed in tumor samples, including in 54% of HNSC and 78% of kidney renal clear cell carcinoma patients." (PMID 25484917, 2014). "Furthermore, we specifically analyzed thyroid follicular cells and tumor cells to determine the differences in TDSs and the expression of SETMAR in these groups of cells." (PMID 38900084, 2024). "In this paper, we aimed at defining the expression pattern of SETMAR isoforms in GB samples coming from cohorts of patients with different clinical profiles and from different regions of the tumor segregated as central necrosis, tumor, and perilesional zones." (PMID 35047379, 2021). "Similarly, our results indicated that SETD2, SETD5, and SETMAR were frequently deleted in ccRCC and they were located at 3p, implying their potential roles as tumor suppressors." (PMID 30755832, 2019). "Similar to the expression pattern of SETMAR, the expression of SMARCA2 was also reduced in relatively poorly differentiated tumor tissues." (PMID 38900084, 2024). "In contrast to SETMAR protein isoforms, snRNP70, OLIG2 and PTN protein levels were lower inside the necrotic area, while being detected at higher levels within the tumor region." (PMID 35047379, 2021). "We focus our interest on SETMAR expression in GBM, a tumor model known for its resistance to both radio and chemotherapy, a characteristic that is a priori coherent with the known biological activities of SETMAR." (PMID 28038463, 2017). "We formally demonstrated that SETMAR levels increase globally within the tumor, compared to surrounding tissues, regardless of the pattern of differential alternative splicing of SETMAR isoforms." (PMID 35047379, 2021). "The amount of SETMAR protein in tumor tissues was only addressed in GB and colon cells, while other studies only focused on mRNA levels despite a lack of correlation between SETMAR mRNA and protein levels." (PMID 35047379, 2021).
infection (1 paper, 2019). The state of being infected such as from the introduction of a foreign agent such as serum, vaccine, antigenic substance or organism. "HDAC5, KDM2B, EZH1, PRDM2, SETMAR, SMYD4 and USP12 were differentially expressed at all time points post-infection (excluding 2 hpi)." (PMID 30728374, 2019).
SETMAR also shares sentences with these, for which no sentence is quoted: leukemia (3 papers); cervical carcinoma (1); hematologic neoplasms (1); lung squamous cell carcinoma (1); lymph node metastasis (1); myopia (1); rectum cancer (1); thyroid tumor (1).